NPHP3 (nephrocystin 3)
Diseases named in the same sentence as NPHP3 in open-access papers (continued):
Sharing a sentence is not in itself a finding about the gene and the disease.
cancer (6 papers, 2020 to 2024). A tumor composed of atypical neoplastic, often pleomorphic cells that invade other tissues. "In this study, we investigated whether cancer cell viability was regulated by NPHP3 expression-associated primary cilium formation via ROS-induced HIF-1α under SD conditions in HeLa human cervical cancer cells." (PMID 36498831, 2022). "In this study, our data demonstrated that PC formation regulates cancer cell viability and growth by NPHP3 expression through ROS-induced ERK activation and HIF-1α stabilization under SD conditions." (PMID 36498831, 2022). "Our data demonstrated that PC formation regulated cancer cell viability under SD condition via NPHP3 expression by ROS-induced ERK activation and HIF-1α stabilization." (PMID 36498831, 2022). "NPHP3 also controls cancer cell viability via PC formation under SD conditions." (PMID 39408701, 2024). "NPHP3 also controls cancer cell viability via PC formation under serum-deprived (SD) conditions." (PMID 39408701, 2024). "Further studies are required to clarify whether NPHP3 moves between the PC and the cortical cell surface when cancer cells become resistant." (PMID 39408701, 2024). "The data suggested that SD-induced Nrf2 and HIF-1α could be related to NPHP3 expression leading to the regulation of cancer cell death." (PMID 36498831, 2022). "Taken together, the results imply that PC formation in cancer cells could be controlled by NPHP3 expression through ROS-induced HIF-1α and ERK activation under SD conditions." (PMID 36498831, 2022). "Thus, the relevance of HIF-1α and the signaling molecules involved in PC formation and NPHP3 expression to regulate cancer cell viability are further clarified." (PMID 36498831, 2022). "It suggests that cancer cell viability under SD conditions could be maintained by NPHP3 expression to regulate PC formation." (PMID 36498831, 2022). "However, no information regarding the role of NPHP3-associated PC formation to cancer cell viability has been reported." (PMID 36498831, 2022). "Here, we investigated whether cancer cell viability is regulated by NPHP3-mediated PC formation." (PMID 36498831, 2022). "However, no information regarding the role of HIF-1α on NPHP3-associated PC formation and cancer cell survival has been reported." (PMID 36498831, 2022). "Collectively, cancer cell survival following VBL treatment is regulated by PC formation via AATF-mediated expression of IFT88 and NPHP3." (PMID 39408701, 2024). "Genes and AS events enrolled in the comprehensive prognostic signature included RHOT1 (ES), SH3KBP1 (AP), AGTRAP (AA), PACS2 (AP), RBPMS (AT), B3GNTL1 (AP), MOBP (AT), NPHP3 (ES), ABCC5 (RI), FKTN (ES) and FKBP8 (AA), many of which are known to play important roles in cancer biology." (PMID 32467664, 2020).
tumor (6 papers, 2019 to 2024). "It suggests that Tβ4 could be associated with the localization and the expression of NPHP3, which modulates the formation of primary cilia in tumor cells." (PMID 31048733, 2019). "Our results showed that SD-activated ERK controlled NPHP3 transcription and PC formation, leading to the regulation of tumor cell viability and growth." (PMID 36498831, 2022). "For instance, thymosin beta-4 interacting with NPHP3 regulates tumor growth as well as PC formation." (PMID 36498831, 2022). "Nephronophthisis 3 (NPHP3) has interacted with thymosin beta-4 to regulate PC formation and tumor growth." (PMID 36498831, 2022). "NPHP3, one of the ciliary proteins, regulated PC formation and interacted with thymosin beta-4 to control tumor growth." (PMID 36498831, 2022). "It suggests that Tβ4 could regulate NPHP3 expression leading to modulate primary cilia formation in tumor cells." (PMID 31048733, 2019). "This work suggests that cooperation of Tβ4 and NPHP3 may be required for primary cilia formation in tumor cells." (PMID 31048733, 2019). "We found that the expression of NPHP3, DVL1, and DVL3 was significantly higher and the expression of ANKS6 was significantly lower in the primary tumor in comparison to the normal solid tissue." (PMID 39596188, 2024). "Our findings suggest that cooperation of NPHP3 and IFT88 may be required for PC formation via AATF binding to their promoters in tumor cells and underscore the need for further investigation of the involvement of AATF in the metastasis of ciliated tumor cells." (PMID 39408701, 2024). "We assessed the correlation of INVS and genes of interest in its interactome (NPHP3, DVL1, DVL3, and ANKS6) with tumor immune infiltration and expression using different algorithms (XCELL, TIMER, QUANTISEQ, EPIC, CIBERSORT, CIBERSORT-ABS, and MCPCOUNTER) by using GEPIA." (PMID 39596188, 2024).
cardiac disease (1 paper, 2016). "Among these 4 genes, TTN was the most likely cardiac disease associated gene while lack of evidence for NPHP3, DNAI1, and MUC5B genes existed." (PMID 28018021, 2016).
NPHP3 also shares sentences with these, for which no sentence is quoted: cyst (3 papers); renal dysplasia (2); Alport syndrome (1); attention deficit-hyperactivity disorder (1); chronic tubulointerstitial nephropathy (1); ciliary dyskinesia (1); collagenopathies (1); Dent disease (1); Fanconi anemia (1); genetic disease (1); homocysteinemia (1); Hyperechogenic kidneys (1); Leber congenital amaurosis (1); liver cirrhosis (1); Lowe syndrome (1); lung adenocarcinoma (1); melanoma (1); Methylmalonic aciduria (1); Nystagmus (1); oculomotor nerve disorders (1); Periportal fibrosis (1); renal failure (1).